USP10 (ubiquitin specific peptidase 10)
Description:
Does not deubiquitinate MDM2. Plays a key role in 40S ribosome subunit recycling when a ribosome has stalled during translation: acts both by inhibiting formation of stress granules, which store stalled translation pre-initiation complexes, and mediating deubiquitination of 40S ribosome subunits. Acts as a negative regulator of stress granules formation by lowering G3BP1 and G3BP2 valence, thereby preventing G3BP1 and G3BP2 ability to undergo liquid-liquid phase separation (LLPS) and assembly of stress granules. Promotes 40S ribosome subunit recycling following ribosome dissociation in response to ribosome stalling by mediating deubiquitination of 40S ribosomal proteins RPS2/us5, RPS3/us3 and RPS10/eS10, thereby preventing their degradation by the proteasome. Part of a ribosome quality control that takes place when ribosomes have stalled during translation initiation (iRQC): USP10 acts by removing monoubiquitination of RPS2/us5 and RPS3/us3, promoting 40S ribosomal subunit recycling. Deubiquitinates CFTR in early endosomes, enhancing its endocytic recycling. Involved in a TANK-dependent negative feedback response to attenuate NF-kappa-B activation via deubiquitinating IKBKG or TRAF6 in response to interleukin-1-beta (IL1B) stimulation or upon DNA damage. Deubiquitinates TBX21 leading to its stabilization. Plays a negative role in the RLR signaling pathway upon RNA virus infection by blocking the RIGI-mediated MAVS activation. Mechanistically, removes the unanchored 'Lys-63'-linked polyubiquitin chains of MAVS to inhibit its aggregation, essential for its activation.
Synonyms: KIAA0190; UBPO
Tractability: PROTAC: UniProt records ubiquitination sites on it; ubiquitination databases record sites on it; its protein half-life has been measured; a small molecule that binds it is known.
Target class: Cysteine protease; Cysteine protease CA clan; Protease; Enzyme; Cysteine protease C19 family
Gene: Protein-coding gene on chromosome 16 (84,699,971 to 84,779,926, forward strand). Ensembl gene ENSG00000103194.
Subcellular location: Cytoplasm; Nucleus; Early endosome
Subcellular location (Human Protein Atlas): Cytosol; Nucleoplasm
Pathways (Reactome):
DNA Repair: Termination of translesion DNA synthesis
Metabolism of proteins: Ub-specific processing proteases
Gene Ontology:
Molecular function: cysteine-type deubiquitinase activity; cysteine-type endopeptidase activity; molecular function inhibitor activity; protein binding; RNA binding; transmembrane transporter binding
Biological process: cellular response to interleukin-1; DNA damage response; innate immune response; monoubiquitinated protein deubiquitination; negative regulation of canonical NF-kappaB signal transduction; negative regulation of stress granule assembly; protein deubiquitination; regulation of autophagy; rescue of stalled ribosome; translesion synthesis
Cellular component: cytoplasm; cytosol; cytosolic ribosome; early endosome; nucleoplasm; nucleus; protein-containing complex
Genetic constraint (gnomAD): Loss-of-function variants: 19 observed, 68.96 expected, observed/expected ratio (o/e) 0.28, 90% interval 0.19 to 0.4. The upper end of that interval is the gene's LOEUF score, 0.4, which puts it in group 1 of 6, group 1 being the genes least tolerant of losing a copy. Missense variants: 999 observed, 982.86 expected, observed/expected ratio (o/e) 1.02, 90% interval 0.96 to 1.07. Synonymous variants: 450 observed, 382.7 expected, observed/expected ratio (o/e) 1.18, 90% interval 1.09 to 1.27.
Homologues: Orthologues: chimpanzee USP10 (99% identical), macaque USP10 (98% identical), dog USP10 (89% identical), pig USP10 (85% identical), rat Usp10 (84% identical), mouse Usp10 (83% identical), rabbit USP10 (77% identical), guinea pig USP10 (77% identical), tropical clawed frog usp10 (71% identical), zebrafish usp10 (61% identical). Paralogues in human: USP9X (21% identical), USP32 (19% identical), USP9Y (19% identical), USP8 (18% identical), USP24 (18% identical), USP19 (18% identical), USP4 (16% identical), USP15 (16% identical), USP35 (16% identical), USP36 (15% identical), USP38 (15% identical), USP42 (15% identical), and 59 more.
Diseases named in the same sentence as USP10 in open-access papers:
USP10 is named in the same sentence as 117 diseases in open-access papers, as found by Europe PMC text mining. Sharing a sentence is not in itself a finding about the gene and the disease. The quoted sentences say what the papers report.
breast cancer (38 papers, 2012 to 2026). A primary or metastatic malignant neoplasm involving the breast. "Taken together, these results show USP10 is upregulated in a fraction of breast cancers and is linked to a more malignant phenotype." (PMID 40991650, 2025). "Nevertheless, we have conclusively demonstrated that genetic KO of USP10 or enzymatic inhibition of USP10 using a ubiquitin-binding variant decreases PI3K pathway activation in PIK3CA-mutant breast cancers." (PMID 40991650, 2025). "Additional work will be needed to investigate the detailed underlying mechanism by which USP10 contributes to paraptotic cell death in malignant breast cancer cells." (PMID 30894572, 2019). "USP10 is linked to PI3Ki resistance in breast cancers with high PTEN expression." (PMID 40991650, 2025). "Notably, USP10 expression was significantly enriched in cluster 1, which is defined by a distinct transcriptional signature associated with breast cancer, as evidenced by the expression of key breast cancer–related biomarkers." (PMID 40991650, 2025). "We investigated if the oncogenic role of USP10 we identified is a relevant factor in human breast cancer and PI3Ki resistance." (PMID 40991650, 2025). "USP10 has been shown to positively correlate with the Yes1-associated transcriptional regulator (YAP1 or YAP), thereby promoting breast cancer progression and metastasis." (PMID 41294885, 2025). "This point requires additional validation if USP10 or GSK3β inhibitors are to be used in the treatment of PI3K-mutant breast cancers." (PMID 40991650, 2025). "Downregulation of GSK3β or USP10 resensitizes PI3Ki-resistant breast cancer models and patient-derived organoids to PI3K inhibition and induces tumor regression." (PMID 40991650, 2025). "Taken together, our results indicate USP10 is a critical regulator of PI3K signaling in breast cancer." (PMID 40991650, 2025). "Mechanistically, A‐1331852‐induced destabilization of ERα and USP10 abrogates both transcriptional oncogenesis and metabolic adaptation, representing a dual attack on HR+ breast cancer's core vulnerabilities." (PMID 41047477, 2025). "To investigate the influence of USP10 on tumor progression through the regulation of B7‐H4 in vivo, we engineered murine 4T1 breast cancer cell lines to alter USP10 expression." (PMID 39206932, 2024). "IGF2BP1 is stabilized by deubiquitination mediated by Ubiquitin-Specific Peptidase 10 (USP10), resulting in its elevated expression in breast cancer." (PMID 39342406, 2024). "In clinical samples, USP10 levels correlated with IGF2BP1 and CPT1A levels, and breast cancer patients with high levels of USP10, IGF2BP1, and CPT1A had the worst outcome." (PMID 36632454, 2023). "The results showed that USP10 expression in breast cancer, cervical cancer, colorectal cancer, gastric cancer, head and neck cancer, leukemia, lung cancer, lymphoma, melanoma, myeloma, and prostate cancer was higher than that in normal tissues." (PMID 35433424, 2022). "High USP10 expression in prostate cancer, breast cancer, non-small cell lung cancer, colon cancer, and melanoma is associated with poor patient prognosis." (PMID 35433424, 2022).
breast cancer (continued). "USP10 protein expression was higher in breast cancer, liver cancer, lung cancer, colorectal cancer, kidney cancer, prostate cancer, stomach cancer, skin cancer, cerebrum cancer, esophagus cancer, and uterus cancer tissues than in normal tissues." (PMID 35433424, 2022). "Some studies have found that USP10 acts as an oncogene in glioblastoma multiforme and breast cancer, while other studies have shown that USP10 plays tumor-suppressive roles in colon cancer and gastric carcinoma." (PMID 34967276, 2022). "In breast cancer cells, USP10 has been identified as a critical regulator of the phosphoinositide 3-kinase (PI3K) pathway." (PMID 33277473, 2020). "UCHL1 expression was frequently downregulated or silenced in breast cancer cell lines, but broadly expressed in all the normal adult tissues and mammary epithelial cell lines, while USP10 is widely expressed in both normal tissues and breast cancer cell lines." (PMID 22279545, 2012). "Moreover, in line with our results for PDX98 and PDX313 and our single-cell and spatial analyses, within The Cancer Genome Atlas (TCGA) database (TCGA cBioportal) 20% of patients with breast cancer had upregulation of USP10 mRNA levels." (PMID 40991650, 2025). "USP10 is upregulated in breast cancer and contributes to PI3Ki resistance." (PMID 40991650, 2025). "Since the PI3K pathway is frequently hyperactivated in breast cancer typified by a high frequency of PIK3CA mutations, we analyzed the effect of USP10 depletion in the breast cancer cell lines MCF7 (PIK3CA-E545K) and T47D (PIK3CA-H1047R), which both harbor activating mutations in PIK3CA." (PMID 40991650, 2025). "Therefore, we sought to confirm our observed inhibitory effect of USP10 KD on PI3K signaling in breast cancer cells through 4 independent methods." (PMID 40991650, 2025). "Taken together, these data suggest USP10 may support PI3Ki resistance in breast cancers that retain high levels of PTEN." (PMID 40991650, 2025). "Suppression of USP10/B7‐H4 proteolytic axis could be a novel strategy to reduce B7‐H4 and improve immune response in breast cancer treatment." (PMID 39206932, 2024). "This analysis revealed a significant upregulation of USP10 in breast cancer cases." (PMID 39206932, 2024). "Indeed, several malignancies like certain breast cancers and glioblastoma display prominent USP10 overexpression." (PMID 37371055, 2023). "Additionally, USP10 is overexpressed in breast cancer, and overexpression correlates with tumor progression and poor overall patient survival." (PMID 33277473, 2020). "Consistent with our screening results on the effect of USP10 siRNA, pretreatment with spautin-1, a specific inhibitor of USP10, markedly inhibited curcumin-induced morphological changes of mitochondria and subsequent paraptotic cell death in various breast cancer cells." (PMID 30894572, 2019). "As with USP10, additional studies in breast cancer are needed for USP25." (PMID 25606592, 2014). "USP10 also demonstrates a dual role depending on the cancer type; it has been known to act as a tumor suppressor in gastric carcinoma, hepatocellular carcinoma, and intestinal adenocarcinoma, but function as oncogenic function in prostate cancer, breast cancer, and acute myeloid leukemia." (PMID 41362702, 2025). "USP10 (ubiquitin-specific peptidase 10), a deubiquitinating enzyme that plays a critical role in different cellular processes by regulating the removal of ubiquitin from target proteins, has been shown to be involved in the regulation of curcumin-induced paraptosis in breast cancer cells." (PMID 39519031, 2024).
breast cancer (continued). "Notably, the expression of USP10 had a marked effect on the prognosis of six types of cancers, including brain cancer, skin cancer, lung cancer, ovarian cancer, colorectal cancer, and breast cancer." (PMID 35433424, 2022). "Growing evidence has shown that USP10 plays important tumor-suppressor roles in different cancers, such as colorectal cancer, non-small-cell lung cancer, small intestinal adenocarcinoma, epithelial ovarian cancer, colorectal cancer, renal-cell carcinoma, breast cancer, and gastric cancer." (PMID 35627217, 2022). "USP10 is overexpressed in multiple malignancies including certain breast cancers and glioblastoma, while it is under-expressed in other malignancies including gastric carcinoma, and colon and lung cancers, suggesting that the role of USP10 in cancer is context-dependent." (PMID 33277473, 2020). "In fact, USP10 has abnormal expression and plays important roles in a variety of tumor cells growth such as breast cancer, glioblastoma multiforme (GBM), adult T-cell leukemia (ATL) and pancreatic cancer, although the underlying mechanisms remain largely unknown." (PMID 27003362, 2016). "Conversely, deubiquitinase USP10 and USP9X stabilize YAP and promote cell growth and survival in HCC and breast cancer." (PMID 39968498, 2025). "While several DUBs, such as USP10 and USP9X, have been reported to affect YAP1 ubiquitination in HCCs and breast cancers respectively, the deubiquitinating enzyme responsible for YAP1 regulation in CRC has remained unidentified." (PMID 39968498, 2025). "To determine the relevance of PTEN stability by USP10 in patients, we performed immunohistochemical staining of PTEN and USP10 on sequential sections of 107 primary or metastatic breast cancer samples." (PMID 40991650, 2025). "We next analyzed publicly available single-cell sequencing data comparing PTEN expression with USP10 expression and upregulation of PI3K gene expression signatures in breast cancer." (PMID 40991650, 2025). "To assess the potential of targeting the USP10/B7‐H4 axis to sensitize breast cancer cells to SG, we conducted coculture assays with MDA‐MB‐468 and HCC70 where B7‐H4 or USP10 was knocked down, followed by SG treatment." (PMID 39206932, 2024). "USP10 can bind to, deubiquitinate, and stabilize IGF2BP1, resulting in its higher expression level in breast cancer." (PMID 36632454, 2023). "Respectively, USP10 and OTUB2 were recently reported as the candidate proteins that deubiquitinated and stabilized YAP/TAZ in the liver and breast cancer models." (PMID 36470870, 2022). "Recent reports have documented that TAZ can be directly deubiquitinated and stabilized by USP1, USP10, OTUB2 and JOSD2 in hepatocellular carcinoma, breast cancer and cholangiocarcinoma." (PMID 35931679, 2022). "An analysis of differential USP gene expression in breast cancer found greater than threefold overexpression of USP9X, USP10 and USP25 in human breast cancer tissue as compared with adjacent normal tissue." (PMID 25606592, 2014). "USP10 stimulates proliferation in ER-α-positive breast cancer cells and ER-α-negative breast cancer cells by enhancing the stability of TCF4 protein." (PMID 41294885, 2025). "Indeed, USP10 and OTUB2 were recently reported as the candidate proteins that deubiquitinated and stabilized YAP/TAZ in the liver and breast cancer models, respectively." (PMID 35906484, 2023).
breast cancer (continued). "Our correlation study using the human breast cancer tissues also revealed a negative association between KCTD10 and SLC7A11, and a positive association between USP10 and SLC7A11 at both mRNA and protein levels, indicating a pathological relevance of our finding." (PMID 38959043, 2024). "Also, circPOKE exists in the exosomes of breast cancer cells and can reduce its binding with snail (the crucial regulator of the EMT process) by directly binding to USP10 protein, thus inhibiting the metastasis of breast cancer cells rather than proliferation." (PMID 39584047, 2024). "To date, in addition to blood-related cancers, USP10 also plays oncogenic roles in many solid tumors including hepatocellular carcinoma (HCC), colon cancer, renal-cell carcinoma (RCC), non-small-cell lung cancer (NSCLC), prostate cancer (PCa), esophageal cancer, breast cancer, and melanoma." (PMID 35627217, 2022).